PPARGC1A (PPARG coactivator 1 alpha)
Diseases named in the same sentence as PPARGC1A in open-access papers (continued):
Sharing a sentence is not in itself a finding about the gene and the disease.
prediabetes (3 papers, 2013 to 2023). "Therefore, a metabolic challenge could be necessary to unmask the association between PPARGC1A expression and prediabetes in the FDR subjects included in this study." (PMID 23505498, 2013). "Skeletal muscle gene expression of PPARGC1A and genes involved in oxidative phosphorylation has been extensively studied in relation to prediabetes and T2D, and increased skeletal muscle expression of PPARGC1A is believed to contribute to improved insulin sensitivity." (PMID 23505498, 2013).
psoriasis (3 papers, 2021 to 2024). An autoimmune condition characterized by red, well-delineated plaques with silvery scales that are usually on the extensor surfaces and scalp. "Several psoriasis-related genes were among the associated genes of hsa_skin_088763, including GATA6, SIK2, IL17RD, EGR3, FAS, LRIG1, and PPARGC1A." (PMID 34068434, 2021). "Therapy by blocking IL-23 might not be effective in moderate-to-severe psoriasis patients with high PPARGC1A expression." (PMID 33681365, 2021).
Renal cyst (3 papers, 2020 to 2024). A fluid filled sac in the kidney. "Concordantly, the genes encoding PPARα and estrogen-related receptors (PPARGC1A, PPARA, ESRRA and ESRRG) were all downregulated in renal cysts." (PMID 39000280, 2024).
sarcoma (3 papers, 2012 to 2023). A usually aggressive malignant neoplasm of the soft tissue or bone. "FOXO1 is a well-known TF that, in association with the coactivator PGC-1α (PPARGC1A), activates the gluconeogenic enzyme fructose 1,6-bisphosphatase (FBP), a putative inhibitor of sarcoma growth." (PMID 37834179, 2023).
triple-negative breast carcinoma (3 papers, 2020 to 2022). An invasive breast carcinoma which is negative for expression of estrogen receptor (ER), progesterone receptor (PR), and human epidermal growth factor receptor 2 (HER2). "For example, the key FAO transcriptional regulator, peroxisome proliferator-activated receptor gamma coactivator 1 alpha (PPARGC1A, also known as PGC-1α) is highly expressed in triple negative breast cancer." (PMID 34217300, 2021). "Analysis of gene expression using bc-GenExMiner showed that the mRNA levels of FABP, ADIPOQ, PPARG, CD36, PPARGC1A, and CREBBP were significantly lower in basal-like and triple-negative breast cancer (TNBC) cells than in non-basal-like and non-TNBC cells." (PMID 36114448, 2022).
vitiligo (3 papers, 2017 to 2024). Generalized well circumscribed patches of leukoderma that are generally distributed over symmetric body locations and is due to autoimmune destruction of melanocytes. "In addition, putative target genes of miR-211 such as PPARGC1A, RRM2, and TAOK1 are highly upregulated in Vitiligo, which is a pigmentation disorder." (PMID 39409187, 2024).
anaemia (2 papers, 2021). "Although limited sample measurements of PFOS, PFOA, TG, and FA were performed due to anaemia during pregnancy, interactions between PFOS levels and the PPARGC1A or PPARD genotype affecting FA levels were observed in the original data." (PMID 33976266, 2021).
asbestosis (2 papers, 2025). A lung disorder caused by inhalation of asbestos fibers. "Although its transcriptional induction has many points of regulation, the modulation of Ppargc1a transcription in macrophages in asbestosis or established fibrosis has not been determined." (PMID 40208691, 2025).
emphysema (2 papers, 2021 to 2023). "In this study, we found that the expression level of Dio2 increased and Ppargc1a decreased in elastase-induced COPD mice (emphysema-dominant COPD model) but not in C57BL/6J-βENaC-Tg mice." (PMID 38247455, 2023).
essential tremor (2 papers, 2018 to 2020). A relatively common disorder characterized by a fairly specific pattern of tremors which are most prominent in the upper extremities and neck, inducing titubations of the head. "An essential tremor SNP (rs3794087 of SLC1A2) is associated with a decreased risk of PD in the Eastern Han Chinese population, while rs9652490 (LINGO1) and rs17590046 (PPARGC1A) do not show an association." (PMID 31755235, 2020).
experimental autoimmune encephalomyelitis (2 papers, 2019 to 2021). An autoimmune demyelinating disease of the central nervous system that is produced experimentally in animals by the injection of homogenized brain or spinal cord in Freund's adjuvant. "Accordingly, neuronal deletion of Ppargc1a aggravated neurodegeneration during experimental autoimmune encephalomyelitis, while neuronal overexpression of Ppargc1a ameliorated it." (PMID 33565962, 2021). "Neuronal Ppargc1a levels determine neuronal injury and clinical disability in experimental autoimmune encephalomyelitis (EAE)." (PMID 33565962, 2021).
gestational diabetes (2 papers, 2015 to 2024). Carbohydrate intolerance first diagnosed during pregnancy. "PPARGC1A has been confirmed in many studies to be involved in blood glucose regulation and the occurrence and development of gestational diabetes in patients with gestational diabetes." (PMID 39060963, 2024).
hypertrophic cardiomyopathy (2 papers, 2008 to 2009). A condition in which the myocardium is hypertrophied without an obvious cause. "Also, the PPARGC1A Gly482Ser polymorphism has been associated with hypertrophic cardiomyopathy." (PMID 19077249, 2008).
Intellectual disability (2 papers, 2019 to 2024). "Although individuals with intellectual disability were excluded from our study, our results suggest that methylation ratio of the PPARGC1A is associated with IQ raher than ADHD per se." (PMID 31379624, 2019).
keloid (2 papers, 2021 to 2022). An irregularly shaped, elevated mark on the skin caused by deposits of excessive amounts of collagen during wound healing. "PPARGC1A, PPARG, PLIN1, LPL, ABHD5, lncRNA PART1, lncRNA ENTPD3-AS1 in trunk keloid and DGAT2 in ear keloid showed decreased trend under paired comparation." (PMID 35677827, 2022).
leukemia (2 papers, 2017 to 2024). A malignant (clonal) hematologic disorder, involving hematopoietic stem cells and characterized by the presence of primitive or atypical myeloid or lymphoid cells in the bone marrow and the blood. "Furthermore, the circRNA-miRNA-mRNA interaction network of hsa_circ_0004277 from cytoscape analysis offered us several downstream gene-candidates, among which SH3GL2 and PPARGC1A were reported to be involved in several solid tumors, and SH2B3 especially as “a new leukemia predisposition gene”." (PMID 28282919, 2017).
Ascites (1 paper, 2019). Accumulation of fluid in the peritoneal cavity (between the layers of the peritoneum that lines the abdomen). "Probably, the increased activity of PPARGC1A in breast muscle during sexual maturity could play a role in enhancing mitochondrial respiratory capacity which attenuates the development of ascites in SUS males." (PMID 30870420, 2019).
biliary cirrhosis (1 paper, 2013). "Key transcription factor Ppargc1a was significantly down-regulated in both tissues but particularly in adipose; which was accompanied by a 2-fold reduction in hepatic expression of the Cl(−)/HCO (−) anion exchanger 2 (Slc4a2), which is critically involved in the development of biliary cirrhosis." (PMID 23783067, 2013).
Dystonia (1 paper, 2021). An abnormally increased muscular tone that causes fixed abnormal postures. "This is in accordance with the global Ppargc1a knockout mice that showed neurological symptoms such as myoclonus, dystonia, and limb clasping that was attributed to axonal striatal degeneration, although we were not able to detect this phenotype in our neuron-specific Ppargc1a knockout mice." (PMID 33565962, 2021).
Lipedema (1 paper, 2023). Disorder of adipose tissue characterized by symmetric and bilateral enlargement of the lower extremities due to abnormal deposition of subcutaneous fat often in obese women. "In none of the conditions, PPARGC1A expression was altered, suggesting that mitochondrial biogenesis is normal during lipedema disease progression." (PMID 37575263, 2023).
mastitis (1 paper, 2022). Inflammation of breast tissue during lactation or postpartum due to an obstructed duct or infection. "Some positively selected genes were reported to be associated with lactation function and disease resistance, such as the butterfat rate [PPARGC1A], milk production [B4GALT1], immunity [IL2 and NFATC3], and mastitis resistance [ITSN2]." (PMID 35422847, 2022).
microcephaly (1 paper, 2020). A congenital or acquired developmental disorder in which the circumference of the head is smaller than normal for the person's age and sex. "We identified the candidate genes PPARGC1A, CTBP1, TRIO, TERT, and CCT5 that are associated with the neuropsychomotor delay, microcephaly, and neurological alterations found in our patient." (PMID 32625234, 2020).
rectal cancer (1 paper, 2017). A primary or metastatic malignant neoplasm that affects the rectum. "In the present study, interaction between diet-associated inflammation and a PPARGC1A genetic variant was slightly stronger among those with rectal cancer." (PMID 28051997, 2017).
Spinocerebellar ataxia type 3 (1 paper, 2020). "For instance, G. inflata extract has been documented to reduce spinocerebellar ataxia type 3 (SCA3) by increasing the nuclear factor erythroid 2-related factor 2-antioxidant-responsive elements (NFE2L2-ARE), coactivator 1α (PPARGC1A), and the peroxisome proliferator-activated receptor γ activities." (PMID 32106571, 2020).
vitamin B12 deficiency (1 paper, 2023). A disease characterized by low serum levels of vitamin B12, either inherited or acquired. "Interestingly, Ppargc1a is activated by Sirt1 diacylation, whose expression, in turn, is downregulated in vitamin B12 deficiency owing to reduced activity of methionine synthase." (PMID 37369025, 2023).
tumor (413 papers, 2006 to 2026). "PPARGC1A is closely linked to the immunoregulatory functions of TAMs, particularly the suppression of proinflammatory signals within the tumor microenvironment." (PMID 40564032, 2025). "In response to tumour growth, eWAT exhibited higher expression of Ucp1 and Ppargc1a, encoding UCP1 and PGC1α, respectively, which are involved in the adipocyte metabolic switch to a thermogenic fat‐burning state termed ‘browning’." (PMID 39971710, 2025). "Our results and those of other studies both validated the decreased expression of PPARGC1A in tumour cells, but paradoxically, some studies showed that PPARGC1A is associated with the proliferation of tumour cells." (PMID 38045683, 2023). "PPARGC1A had oncogenic and tumor suppressive features, and high and low levels of PPARGC1A expression associated with the prognosis of different cancers." (PMID 37903974, 2023). "This correlation suggests that PPARGC1A may influence macrophage polarization, potentially reducing the pro-tumoral M2 phenotype, which is often associated with tumor progression in HCC." (PMID 40564032, 2025). "In addition, PPARGC1A is associated with resting and activated mast cells, suggesting its involvement in regulating the tumor microenvironment." (PMID 40564032, 2025). "Notably, the gene PPARGC1A was the most significantly down-regulated gene from pT1-2 to pT3-4 RCC which correlated with loss of mitochondrial function in tumour-infiltrating T-cells evident at this tumour stage." (PMID 37940720, 2023). "In summary, loss of PPARGC1A due to germline PPARGC1A variants might stimulate tumor development by giving tumor cells a metabolic advantage or weakening immune surveillance, or both." (PMID 35625955, 2022). "Previous study had reported that the expression of PPARGC1A was negatively associated with some immune cells, which means that PPARGC1A may be responsible for regulating the immune components of tumor microenvironment." (PMID 36506326, 2022). "Moreover, PPARGC1A is also associated with the dysfunction of tumour-specific T cells." (PMID 38045683, 2023). "Several hypoxia genes with high-frequency somatic mutations were identified, including CDKN1A, PPARGC1A, and AKAP12, which showed unequivocal associations with tumor initiation." (PMID 38806990, 2025). "Activation of the Heterogeneous Nuclear Ribonucleoprotein D (hnRNP D)/PPARG Coactivator 1 Alpha (PGC-1α) module enhances angiogenesis and invasion, whereas FOXO1-driven acetylation following SIRT1 loss suppresses tumor growth and promotes apoptosis." (PMID 41425553, 2025). "Peroxisome proliferator activated receiver gamma coactivator 1 alpha (PPARGC1A) is a key transcription coactivator that can regulate oxidative phosphorylation to promote tumor cell metastasis." (PMID 37903487, 2024). "Results showed that the mRNA levels of BNIP3, CYCS, RRAGD, CD44, EIF4E, MAP4K1, and LIN28B were higher in tumor samples, whereas the mRNA levels of PPARGC1A and FLT3 were higher in normal samples." (PMID 38468074, 2024). "Among all the 12 signature genes in the risk score model, we found that most of the genes were statistically different between tumor tissues and normal controls, and in particular, two genes (PPARGC1A and FLT3) were decreased in the tumor tissue." (PMID 38468074, 2024). "They showed that in high expressing PPARGC1A ccRCCs, immune-related signalling and epithelial mesenchymal transition pathways were the most enriched, while in low expressing tumours, metabolic pathways were highly enriched." (PMID 37940720, 2023). "PPARGC1A is known to be a key transcriptional coactivator that coordinates mitochondrial biogenesis and oxidative phosphorylation in tumour cells to induce metastasis." (PMID 37940720, 2023). "This study shows this loss of mitochondrial function in tumour-infiltrating T-cells is most evident at tumour stage pT3-4 which correlated with the down-regulated expression of PPARGC1A in ccRCC tumours at this stage." (PMID 37940720, 2023).
tumor (continued). "It was found that PPARGC1A is downregulated in the tumor tissues, and its low expression predicts poor survival, suggesting its function as a tumor suppressor gene." (PMID 35993051, 2022). "PPARGC1A is responsible for regulating several metabolic pathways necessary for tumor cells to respond to microenvironmental changes, thus promoting tumor growth." (PMID 36465397, 2022). "We observed higher expression levels of Il1rl2, Rbck1, and Ppargc1a in tumor tissues of the CRC group and higher expression levels of Adipoq and Ucn in the colon of the control group." (PMID 36591255, 2022). "Unsurprisingly, given the roles in energy regulation, PPARGC1A impacts tumor progression and growth, but the precise mechanisms are cancer-specific." (PMID 35626007, 2022). "On the other hand, a recent study demonstrated inhibition of PPARGC1A in tumor infiltrating T cells leads to T cell exhaustion and tumor immune escape." (PMID 35625955, 2022). "Accumulating studies have shown that PPARGC1A promoted tumor growth, whereas several studies have found that the lower expression of this gene in COAD is associated with an increased risk of cancer." (PMID 34322151, 2021). "The peroxisome proliferator-activated receptor-γ coactivator 1-α (PPARGC1A) gene also contributes to tumor growth and metastasis in several cancers." (PMID 33441161, 2021). "A previous study had reported that low levels of PPARGC1A expression were correlated with poor survival, vascular invasion, and large tumor size." (PMID 34660596, 2021). "In various malignant tumors, including CRC, ascendant expression of PPARGC1A is strongly related to metabolism and advances the growth, distant spread, and chemical resistance of tumor cells." (PMID 33937013, 2021). "Our data also show a trend towards higher expression of PPARGC1A in CTCs compared to primary tumours, although the difference in expression was only statistically significant for BM18 and LuCaP105 models." (PMID 34206049, 2021). "Some of the identified prognostic DE RBPs have been reported associated with tumor progression, such as RBM47, LUZP4, AFF3, PPARGC1A, PPARGC1B, PABPC3, and PNLDC1." (PMID 33224957, 2020). "The higher expression of PPARGC1A was correlated with high tumor purity in CHOL, GBM, KIRC, KIRP, and THCA, while with low stromal scores of BLCA, HNSC, LUSC, and TGCT, which was the opposite to the pattern of PPARGC1B." (PMID 33029111, 2020). "Moreover, tumor-micro-environment heterogeneity and metabolic stressors such as hypoxia can switch PPARGC1A between tumor-suppressive and tumor-promoting roles." (PMID 40564032, 2025). "According to our results, PPARGC1A was underexpressed in tumor tissue samples." (PMID 40900470, 2025). "The positive correlation between PPARGC1A and resting mast cells suggests that it may reduce the tumor-promoting effects of mast cells by maintaining the inactivated state of these cells." (PMID 40564032, 2025). "By modulating the behavior of B cells, HSPA1A and PPARGC1A might affect the antigen presentation process, influencing the activation and function of tumor-specific T cells." (PMID 37993485, 2023). "The presence of this correlation indicates that HSPA1A and PPARGC1A may be involved in creating an immunosuppressive microenvironment favorable for tumor growth and progression." (PMID 37993485, 2023). "Furthermore, Ppargc1a tumor-suppressive effects were fully reversed by ETO administration, confirming that they were FAO-dependent." (PMID 37084728, 2023). "The specific influence of HSPA1A and PPARGC1A on immune B cells implies that these genes might impact the regulatory functions of B cells within the HCC tumor microenvironment." (PMID 37993485, 2023).